KLB (klotho beta)
Description:
Contributes to the transcriptional repression of cholesterol 7-alpha-hydroxylase (CYP7A1), the rate-limiting enzyme in bile acid synthesis. Probably inactive as a glycosidase. Increases the ability of FGFR1 and FGFR4 to bind FGF21 (By similarity).
Synonyms: BKL
Tractability: Antibody: a drug acting on it is in phase 2 or 3 trials; UniProt places it where antibodies can reach, with high confidence; its Gene Ontology location is reachable by antibodies, with high confidence; UniProt predicts a signal peptide or a membrane-spanning region. PROTAC: ubiquitination databases record sites on it. Other modalities: a drug acting on it is in phase 2 or 3 trials.
Safety:
Unwanted effects reported when the protein is acted on. In parentheses: how it was acted on, where the effect was seen, and who reports it.
alcoholism (source: ClinPGx)
Gene: Protein-coding gene on chromosome 4 (39,406,930 to 39,451,533, forward strand). Ensembl gene ENSG00000134962.
Subcellular location: Cell membrane
Subcellular location (Human Protein Atlas): Mid piece; Principal piece
Pathways (Reactome):
Signal Transduction: FRS-mediated FGFR4 signaling; Negative regulation of FGFR4 signaling; PI-3K cascade:FGFR4; PI3K Cascade; PI5P, PP2A and IER3 Regulate PI3K/AKT Signaling; PIP3 activates AKT signaling; Phospholipase C-mediated cascade; FGFR4; RAF/MAP kinase cascade; SHC-mediated cascade:FGFR4; betaKlotho-mediated ligand binding
Disease: Constitutive Signaling by Aberrant PI3K in Cancer
Gene Ontology:
Molecular function: fibroblast growth factor binding; fibroblast growth factor receptor binding; protein binding; hydrolase activity, hydrolyzing O-glycosyl compounds
Biological process: carbohydrate metabolic process
Cellular component: plasma membrane
Genetic constraint (gnomAD): Loss-of-function variants: 45 observed, 89.62 expected, observed/expected ratio (o/e) 0.5, 90% interval 0.39 to 0.64. The upper end of that interval is the gene's LOEUF score, 0.64, which puts it in group 2 of 6, group 1 being the genes least tolerant of losing a copy. Missense variants: 1,123 observed, 1,349.8 expected, observed/expected ratio (o/e) 0.83, 90% interval 0.79 to 0.87. Synonymous variants: 545 observed, 533.25 expected, observed/expected ratio (o/e) 1.02, 90% interval 0.95 to 1.1.
Homologues: Orthologues: chimpanzee KLB (99% identical), macaque KLB (97% identical), pig KLB (87% identical), dog KLB (86% identical), rabbit KLB (85% identical), rat Klb (80% identical), mouse Klb (79% identical), guinea pig KLB (76% identical), tropical clawed frog klb (52% identical), zebrafish klb (43% identical), Drosophila melanogaster CG9701 (16% identical), Caenorhabditis elegans klo-1 (13% identical), and 1 more. Paralogues in human: KL (43% identical), LCT (36% identical), LCTL (20% identical), GBA3 (17% identical).
Diseases named in the same sentence as KLB in open-access papers:
KLB is named in the same sentence as 91 diseases in open-access papers, as found by Europe PMC text mining. Sharing a sentence is not in itself a finding about the gene and the disease. The quoted sentences say what the papers report.
Obesity (44 papers, 2012 to 2025). Accumulation of substantial excess body fat. "Polymorphisms of the KLB gene are associated with obesity, further demonstrating the vital role of this receptor in facilitating FGF21 induced-weight loss." (PMID 39087083, 2024). "Together, these data suggest GCGR agonism mediates part of its weight loss properties through central KLB and has implications for future treatments of obesity and metabolic syndrome." (PMID 33411693, 2021). "The expected outcome of global KLB deficiency was worsened metabolism (i.e. hepatosteatosis, obesity, insulin resistance) under HFD feeding conditions." (PMID 35046901, 2021). "In the Han Chinese, KLB is strongly associated with obesity, the development of NAFLD in the obese population, and hepatic inflammation in NAFLD patients." (PMID 31548436, 2019). "An important finding of our study is the strong association between KLB SNP rs7670903 and obesity in a Han population of East China." (PMID 31548436, 2019). "Such alterations of the FGF21/KLB/FGFR1 signaling pathway and especially mutations of KLB have to be searched in functional HH, like hypothalamic amenorrhea and obesity‐related HH." (PMID 28778954, 2017). "Therefore, the contribution of KLB is associated with increased sensitivity to the beneficial effects of FGF21 on obesity and type 2 diabetes, including regulation of body weight, plasma lipid levels and insulin sensitivity." (PMID 37019912, 2023). "Central KLB in diet-induced obesity and GCGR-mediated weight loss." (PMID 33411693, 2021). "The authors hypothesized that overexpressing KLB from white adipocytes would reduce obesity-associated FGF21 levels, if indeed they were reflective of FGF21 resistance." (PMID 35046901, 2021). "However, the majority of patients with variants in either FGFR1 and KLB exhibit obesity, dyslipidemia, and insulin resistance." (PMID 33210059, 2020). "This hints that KLB may be an important risk gene for NAFLD under the environmental pressure of obesity." (PMID 31548436, 2019). "Most of these studies focused on the regulation of KLB in adipose tissue in the context of obesity; however, limited information is available on the potential modulation of hepatic KLB expression in the context of MASLD." (PMID 40937171, 2025). "Paradoxically, obesity is associated with an increase in serum FGF21 levels and attributed to a reduction in FGFR and KLB expression on adipocytes." (PMID 39087083, 2024). "As both obesity and fasting can also affect inflammation, inflammatory and cellular stress pathways appear to play a key role in regulating KLB expression." (PMID 37260446, 2023). "Pathophysiological factors that alter KLB expression can be grouped into three categories: obesity, fasting, and inflammation." (PMID 37260446, 2023). "The bispecific anti-FGFR1/KLB agonist antibody BFKB8488A designed against it can treat obesity-related metabolic defects by specifically activating the FGFR1/KLB complex." (PMID 36341333, 2022). "One working theory is that obesity-associated increases in FGF21 reflect an FGF21-resistant state due to observed downregulation of FGFR1c and KLB in the liver and WAT, as well as reduced efficacy of recombinant FGF21 (rFGF21) in mice and humans." (PMID 35046901, 2021). "Rikke and colleagues also found overweight/obesity led to decreased KLB but increased FGFR1c expression in WAT." (PMID 34912302, 2021). "We next performed a high fat diet (HFD) feeding time course to identify when eWAT KLB protein levels decrease in relation to increased plasma FGF21 levels during the development of obesity." (PMID 28580290, 2017). "In contrast, two studies reported an obesity-driven increase in KLB expression in the liver." (PMID 37260446, 2023). "FGF21 signaling through KLB in WAT may be primarily related with obesity, as decreased KLB expression was observed in WAT of obese mice, non-human primates fed with high-fat diet, and obese subjects with different levels of abnormal glucose homeostasis." (PMID 34912302, 2021).
Obesity (continued). "Altered DNA methylation in promoters of transcription factor genes (PPARA, KLF15, NR3C1, RORA and ATF4) known to regulate FGF21 expression and its binding receptors and co-factors (FGFR1, FGFR3 and FGFRL1 and KLB) has been revealed in relation to the elevated levels of circulating FGF21 in obesity." (PMID 33670024, 2021). "Initial studies that observed increased FGF21 levels associated with obesity hypothesized that this reflected a state of “FGF21 resistance”, due to modestly decreased expression levels of both KLB and FGFR1 in perigonadal WAT." (PMID 35046901, 2021). "Mice that were deficient in KLB specifically from adipocytes were refractory to the effects of recombinant FGF21 to increase subcutaneous fat mass, suggesting that direct FGF21 signaling to adipocytes is required for subcutaneous fat expansion in obesity." (PMID 35046901, 2021). "In contrast, obesity reduces the expression of KLB in subcutaneous and visceral adipose tissue." (PMID 33381084, 2020). "The mRNA levels of JMJD3 and KLB were decreased, whereas those of Fgfr1 and Fgfr4 were increased, after feeding a HFD, suggesting that decreased expression of KLB may contribute to FGF21 resistance in obesity." (PMID 32042044, 2020). "Furthermore, in adipose tissue, others have reported decreased expression of the FGF21 receptor and/or its co-receptor KLB in diabetes and obesity, suggesting a state of FGF21 resistance." (PMID 29593555, 2018). "Based on our profiling data, we hypothesized that maintaining adipose KLB expression during diet-induced obesity would sensitize mice to endogenous, circulating FGF21, thus preventing FGF21 resistance and potentially improving insulin sensitivity." (PMID 28580290, 2017). "Exercise can reverse dietary obesity-related FGF-21 resistance by the upregulation of FGF receptor-1 (FGFR1) and β-Klotho (KLB)-dependent browning." (PMID 39125923, 2024). "In these animals, exercise was shown to induce transcriptional activation of FGFR1 and KLB in adipocytes, resulting in increased sensibility to FGF21, and hence attenuating obesity-induced metabolic dysfunction." (PMID 37019912, 2023). "Obesity increases expression of FGF21, KLB, FGFR1c, and FGFR3c in the liver, although FGFR2c remains the most highly expressed of FGF21’s receptors in the liver." (PMID 33381084, 2020). "Recent studies suggest that betaKlotho (KLB) and endocrine FGF19 and FGF21 redirect FGFR signaling to regulation of metabolic homeostasis and suppression of obesity and diabetes." (PMID 22442730, 2012). "Moreover, there is evidence suggesting that obesity can induce resistance to FGF21, and obese mice exhibit reduced Klotho beta expression." (PMID 38245790, 2024). "Furthermore, the overexpression of KLB in adipose tissue is sufficient to enhance FGF21 responses and to combat dietary obesity in mice." (PMID 36034414, 2022). "Third, mice with transgenic KLB overexpression are not protected from diet-induced obesity, despite the prediction that they would be more FGF21-sensitive." (PMID 35046901, 2021). "Moreover, it appears that obesity can lead to an FGF21-resistant state and that KLB expression is reduced in obese mice." (PMID 31548436, 2019). "However, conditions such as obesity may lead to FGF21 resistance, and the level of KLB expression may modulate the response to FGF21." (PMID 31548436, 2019).
hepatocellular carcinoma (15 papers, 2012 to 2025). A malignant tumor that arises from hepatocytes. "On the contrary, KLB promotes the growth of bladder cancer and has carcinogenic activity in hepatocellular carcinoma and hepatoblastoma." (PMID 36232594, 2022). "Lastly, we show that both during transient regeneration in response to injury and in hepatomas, the expression pattern of the metabolic co-factor KLB is opposite to that of FGF21 in liver." (PMID 23590285, 2013). "Radio-iodinated FGF19 exhibited an affinity with a Kd value of 303 pM to the FGFR1-KLB complex expressed on the T-Rex 293 cells, and 778 pM to a hepatocellular carcinoma cells expressing FGFR4 and KLB." (PMID 22442730, 2012). "Interestingly, one study on hepatocellular carcinoma showed that a >2-fold increase in KLB gene expression correlates with the development of multiple versus single lesions." (PMID 37958253, 2023). "Hence, we are able to examine the effects of KLB perturbation in an aggressive hepatoma model driven by elevated FGFR4 activity." (PMID 22439738, 2012). "With the coaction of KLB, FGFR4 initiates a growing number of intracellular signaling pathways to target tumor cells, promoting hepatoma cell proliferation and migration and inhibiting tumor cells apoptosis." (PMID 33802841, 2021). "Repression of KLB expression suppressed FGFR4 downstream signaling and significantly inhibited hepatoma cell proliferation." (PMID 22439738, 2012).
diabetes (12 papers, 2012 to 2026). "Another one of the 13 trans genes, KLB, has been found to have reduced expression levels in obesity, diabetes, and lipodystrophy, and impaired browning of white adipose tissue has also been observed with decreased gene dosage of Klb in cold-exposed mice." (PMID 39515300, 2024).
Hepatic steatosis (7 papers, 2020 to 2026). Steatosis is a term used to denote lipid accumulation within hepatocytes. "Utilizing a liver-specific KLB knockdown mouse model, we further confirmed this association, highlighting the profound impact of KLB deficiency in limiting KD’s improvement of hepatic steatosis, suggesting the indispensability of the liver FGF21-KLB pathway." (PMID 38609395, 2024). "Aligned with prior studies, we validated that KD upregulates FGF21 and KLB expression, leading to a reduction in hepatic steatosis." (PMID 38609395, 2024). "Taken together, our data indicate that inhibiting methylation directly at the Klb promoter promotes hepatic FGF15/FGF21/KLB signaling and subsequent fatty acid oxidation, ameliorating hepatic steatosis in mice." (PMID 37282749, 2023). "FGF19 and FGF21 both depend on KLB expression in the CNS to lower hepatic steatosis." (PMID 33414764, 2020). "Thus, liver KLB knockdown impaired the beneficial effect of KD on ameliorating hepatic steatosis, particularly by suppressing lipogenesis, suggesting that FGF21-KLB signaling might be critical for KD-ameliorated hepatic steatosis." (PMID 38609395, 2024). "FGF19 requires KLB expression in the liver to regulate Cyp7a1 expression in mice, while the positive effect of FGF19 and FGF21 on hepatic steatosis was unaffected by adipose and liver specific KLB deletion." (PMID 33414764, 2020).
Insulin resistance (7 papers, 2012 to 2025). Increased resistance towards insulin, that is, diminished effectiveness of insulin in reducing blood glucose levels. "Here, we show that a majority of patients with KLB mutations (9/13) exhibit hypogonadotropic hypogonadism with some degree of metabolic defect (i.e. overweight, insulin resistance, and/or dyslipidemia), consistent with the metabolic role of FGF21/KLB/FGFR1 pathway." (PMID 28754744, 2017). "Therefore, digenic variants in FGFR1 and KLB provide a potential explanation for the subject’s severe insulin resistance and may represent a novel category of insulin resistance syndromes related to FGF21." (PMID 33210059, 2020). "Notably, KD-induced improvement of overweight (30.72 ± 1.49 vs 35.68 ± 3.74 g; P < 0.05), excessive body fat (4.52 ± 0.26 vs 8.06 ± 1.36 g; P < 0.001), hyperglycemia (7.82 ± 0.73 vs 9.90 ± 1.32 mmol/L; P < 0.05), and insulin resistance were diminished after KLB knockdown in mouse livers." (PMID 38609395, 2024).
non-alcoholic fatty liver disease (6 papers, 2014 to 2025). "Three drugs designed to treat nonalcoholic fatty liver disease (NAFLD) were found to effectively target KLB." (PMID 39526184, 2024).
prostate carcinoma (5 papers, 2014 to 2025). A carcinoma that arises from epithelial cells of the prostate gland. "KLB (beta-Klotho) is a tissue restricted single-pass transmembrane protein that acts a co-receptor for FGF family members and has been implicated in prostate cancer." (PMID 25155515, 2014). "In prostate cancer, FGF19/FGFR signaling promotes cancer progression along with the presence of KLa and/or KLb as co-factors." (PMID 29731962, 2018).
steatosis (4 papers, 2019 to 2025). Increased lipid within the cytoplasm of cells. "Lower levels of hepatic KLB protein were significantly associated with higher levels of lobular inflammation (P = .0168) but not with histology- or magnetic resonance imaging–derived scores of steatosis or fibrosis." (PMID 40937171, 2025). "It is still not fully understood if a direct action on hepatocytes contribute to the positive effect of FGF19 and FGF21 on steatosis, but overexpression of an inactive KLB mutant interestingly induces intracellular lipid accumulation in HepG2 and Huh7 cells in vitro." (PMID 33414764, 2020). "The effect on steatosis is likely independent of the FGFR4/KLB complex as a FGF19 variant lacking FGFR1c/KLB activity lack metabolic activity." (PMID 33414764, 2020).
liver cancer (3 papers, 2013 to 2022). An epithelial or non-epithelial malignant neoplasm that arises from the liver. "Several genes previously implicated in liver cancer were discovered by our screening, including KLB, FGF19, FNDC3 and CCND1." (PMID 23776502, 2013). "It was reported that KLB in partnership with FGFR4 induced apoptosis and inhibited tumor cell proliferation in liver cancer, which was correlated with depression of the AKT and mTOR pathways." (PMID 31695781, 2019).
liver fibrosis (3 papers, 2022 to 2026). "Our findings highlight KLB as a promising therapeutic target for hepatic fibrosis in schistosomiasis." (PMID 42154778, 2026). "Our study reveals that KLB suppresses LSEC EMT induced by liver-stage schistosomula and TGFβ1 secretion, thereby inhibiting HSC activation and reducing liver fibrosis." (PMID 42154778, 2026). "In mice infected with S. japonicum, treatment with recombinant KLB protein or AAV8-KLB increased the LSEC population, mitigated EMT in both LSEC and liver tissues, ameliorated hepatic fibrosis, and inhibited TGFβ1 pathway activation." (PMID 42154778, 2026). "Although KLB is known to exert anti-inflammatory functions as a co-receptor for fibroblast growth factor (FGF) in the liver, its role in LSEC EMT and schistosomiasis-induced liver fibrosis was unclear." (PMID 42154778, 2026). "In addition, the down-regulation of KLB was found in the liver tissues of children with nonalcoholic fatty liver disease and adults with liver fibrosis." (PMID 36232594, 2022).
lung carcinoma (3 papers, 2019 to 2022). "We also found that KLB was negatively associated with cell cycle related genes in a lung cancer cohort." (PMID 31695781, 2019). "The literature on the role of KLD in lung cancer is rather limited, though a recent study found that overexpression of KLB inhibits lung tumor growth in vivo." (PMID 35634240, 2022). "To evaluate the prognostic value of KLB in lung cancer patients, we first analyzed the expression and copy number features of KLB in the TCGA provisional LSQ and LADC cohort in Oncomine database." (PMID 31695781, 2019). "For instance, like methylation of the KL promoter region, how epigenetic regulation of KLB expression in relation to FGF19/FGFR4 signaling during lung cancer progression remains an interesting question." (PMID 31695781, 2019). "This may explain the phenomenon that high expression of FGFR1 and low expression of KLB in lung cancer tissues were detected." (PMID 31695781, 2019). "Further researches are need to understand the mechanism of KLB in lung cancer." (PMID 31695781, 2019). "FGFR1 was also highly expressed in NSCLC and promoted tumor formation in lung cancer by interacting with SOX2, Hippo/YAP1 or Hedgehog pathway as our previously work reported 12, 13, 20, while deficiency of KLB did not influence the FGFR1 levels in cultured endothelial cells." (PMID 31695781, 2019). "It appeared that the FGF19/FGFR4 signaling could still function in lung cancer independent of KLB." (PMID 31695781, 2019).
alcohol (2 papers, 2021 to 2023). "As plasma ethanol clearance was not affected in liver-specific FGF21- or neuron-specific KLB-deficient mice, the FGF21-KLB axis is suggested to counteract alcohol intoxication without modulating alcohol catabolism." (PMID 37260446, 2023). "JCAD, KLB, and GCKR have also been associated with alcohol dependence as assessed with the AUDIT." (PMID 34135785, 2021).